KLK6 (kallikrein related peptidase 6)
Diseases named in the same sentence as KLK6 in open-access papers (continued):
Sharing a sentence is not in itself a finding about the gene and the disease.
ovarian carcinoma (continued). "We conclude that KLK6 is transcriptionally upregulated in ovarian cancer, but probably not through alternative mRNA transcript expression, genomic mutation, or steroid hormone induction." (PMID 17242704, 2007). "In this study, we examined whether or not steroid hormones regulated KLK6 expression in ovarian cancer cell lines." (PMID 17242704, 2007). "Even though KLK6 may not be a strong independent prognostic indicator for ovarian cancer, it appears to be a surrogate marker for other clinicopathological variables such as tumour stage, grade, histotype and debulking success." (PMID 17242704, 2007). "Interestingly, the results obtained for KLK14 in this study are comparable to those obtained for KLK3, KLK6 and KLK15 in breast cancer and KLK4, KLK5 and KLK10 in ovarian cancer, in that high expression of these kallikrein genes also correlated with patient prognosis." (PMID 12439719, 2002). "In fact, KLK6 and KLK7 showed almost no expression in normal samples but have previously been found to be early stage biomarkers for ovarian cancer." (PMID 29088818, 2017). "It remains to be elucidated why steroid hormones regulate KLK6 in breast cancer cell lines such as BT474, but not in receptor-positive ovarian cancer cell lines." (PMID 17242704, 2007).
breast carcinoma (33 papers, 2002 to 2026). "Numerous studies have suggested that KLK6 is aberrantly expressed in and is associated with malignant progression in various human cancers including ovarian, colon, lung, and breast cancers." (PMID 36552865, 2022). "KLK6 has been implicated in EMT in breast cancer, in gastric cancer by reducing the expression of E‐cadherin at the transcriptional level, and in colon cancer." (PMID 30980596, 2019). "Concerning the regulation of KLK6 expression, tumor-specific loss in breast cancer is at least in part mediated by epigenetic silencing due to DNA methylation." (PMID 28671620, 2017). "KLK5, for instance, was reported to be downregulated in breast cancer, whereas elevated expression of KLK6, KLK7 and KLK10 has been associated with multiple cancers and poor prognosis in gastric and colorectal cancer." (PMID 29263803, 2016). "Tumor-specific loss of KLK6 expression in breast cancer cells is mediated by epigenetic silencing initiated by hyper-methylation at the proximal promoter." (PMID 25990935, 2015). "In line with our findings in HeLa cells, reactivation of KLK6 in breast cancer cells was associated with prominent down-regulation of Vimentin in the absence of a parallel rise in E-cadherin (unpublished data)." (PMID 25990935, 2015). "However, it remains a major challenge for the future to unravel relevant direct targets for KLK6 proteolysis and affected signaling networks that causally contribute to the observed phenotype in mucosal but also breast cancer cells." (PMID 25990935, 2015). "Finally, we observed a significant association between KLK6 and TGFβ1, which may be one mechanism by which these molecules interact during lactation to influence future breast cancer risk." (PMID 22436421, 2012). "Our findings align with those found in HNSCC and breast cancer, as they demonstrate that higher KLK-6 expression decreases MMP-2 activity and invasion potential in PCa." (PMID 41597241, 2026). "In breast cancer, KLK6 acts as a tumor suppressor gene but its expression is undetectable in metastatic breast cancer due to methylation of the KLK6 gene promoter." (PMID 40168262, 2025). "Our findings align with those in found in HNSCC and breast cancer as it demonstrates that higher KLK-6 expression decreases MMP-2 activity and invasion potential in PCa." (PMID 41509368, 2025). "Zyme appears to play a role in breast cancer, and the cDNA for the KLK6 gene has just been discovered." (PMID 38137332, 2023). "We previously demonstrated that APPI‐4M acts as a functional inhibitor of KLK6‐dependent breast cancer cell migration and invasion." (PMID 37609678, 2023). "Such a study suggested that KLK6 was an epigenetically regulated tumor suppressor in human breast cancer and provided methods for pharmacologic modulation." (PMID 38137332, 2023). "We further demonstrated that APPI‐4M is a functional inhibitor in a cell‐based model of KLK6‐dependent breast cancer invasion." (PMID 37609678, 2023). "In breast cancer, constitutive and inducible expression of KLK6 positively correlated with histone H4 acetylation located in KLK6 upstream sequences." (PMID 32028882, 2020). "KLK6 displays aberrant expression in various types of cancer, including breast cancer, head and neck squamous cell cancer, renal cancer, and colon cancer." (PMID 30980596, 2019). "Analysis of breast cancer clinical datasets showed correlation of KLK6 expression with the expression of BCL members." (PMID 30980596, 2019). "KLK6 expression in breast cancer either above or below the physiological levels has been associated with reduced overall survival of breast cancer patients." (PMID 30980596, 2019). "Kallikrein‐related peptidase 6 (KLK6) is a serine protease normally expressed in mammary tissue and aberrantly regulated in breast cancer." (PMID 30980596, 2019). "The correlation of KLK6 expression with S100 proteins was further investigated in clinical datasets from breast cancer patients." (PMID 30980596, 2019).
breast carcinoma (continued). "Analysis of breast cancer clinical datasets showed correlation (direct or inverse) of KRT expression with KLK6 including an inverse correlation of KLK6 and KRT18." (PMID 30980596, 2019). "On the other hand, overexpression of KLK6 (> 50‐fold higher than normal), characteristic of a subset of breast cancers, promotes primary tumorigenesis and lung metastasis in vivo." (PMID 30980596, 2019). "In silico analysis of breast cancer clinical datasets showed that KLK6 expression inversely correlates with RAB26, RAB17, and RAB30." (PMID 30980596, 2019). "A tumor protective role of KLK6 was demonstrated in breast cancer, where it was identified originally as a putative tumor suppressor due to its down-regulation during metastasis." (PMID 25990935, 2015). "Pampalakis and colleagues demonstrated that restoration of physiological KLK6 levels in breast cancer cell lines reverted the malignant phenotype in vitro and in vivo." (PMID 25990935, 2015). "In contrast, KLK6 expression in breast cancer appears to have a protective role, with elevated expression being linked to reduced proliferation and tumorigenicity." (PMID 26231762, 2015). "Although the principle nature for these cell type specific differences remains elusive, Pampalakis and colleagues claimed that KLK6 regulates EMT in breast cancer cells via the TGF-β pathway." (PMID 25990935, 2015). "KLK6 was initially identified by three different groups, naming it zyme in Alzheimer's disease, protease M in breast cancer, and neurosin in colon adenocarcinoma." (PMID 24669031, 2014). "In breast cancer expression of KLK6 at physiological levels has tumor-suppressor properties, while over-expression results in tumor promotion." (PMID 23216878, 2012). "KLK6 has been reported to interact with the TGFβ1 signal transduction pathway and influence TGFβ1 expression in breast cancer cells." (PMID 22436421, 2012). "The significant changes in KLK6 protein expression during lactation and the report of regulation of KLK6 by methylation in breast cancer cells prompted us to examine KLK6 promoter methylation in cells obtained from breast milk." (PMID 22436421, 2012). "Kallikrein-related peptidase 6 (KLK6) was initially identified by three different groups who named it protease M in breast cancer, zyme in Alzheimer's disease, and neurosin in colon adenocarcinoma." (PMID 19707197, 2009). "Metastatic tumours to the ovary from primary gastrointestinal, endometrial, uterine, or breast cancers expressed low levels of KLK6 that were comparable with benign ovarian tissues." (PMID 17242704, 2007). "Comparing one normal cell line vs two primary tumour cell lines, they identified KLK6 as one of the differentially expressed genes between normal and primary breast cancer (a 2.4-fold increase in cancer)." (PMID 14710225, 2004). "In breast cancer cells, KLK6 has been shown to act as a tumor suppressor." (PMID 41509368, 2025). "Both KLK6 and LIMCH1 expression has been linked to clinical outcome of breast cancer patients." (PMID 38036593, 2023). "Moreover, DNA methylation in the proximal promoter has been shown to repress KLK6 expression in breast cancer." (PMID 35883559, 2022). "In human breast cancer cells, KLK6 expression is silenced via promoter methylation." (PMID 30980596, 2019). "KLK6 silencing in breast cancer cells occurs through promoter methylation." (PMID 30980596, 2019). "The findings promise to aid our understanding of the functional roles of KLK6 in breast cancer and may yield new biomarkers for the cancer types in which KLK6 is known to be aberrantly upregulated." (PMID 30980596, 2019). "S100A4 mediates breast cancer metastasis, and its expression is controlled via the β‐catenin pathway; therefore, high levels of KLK6 could activate the β‐catenin pathway as reported in keratinocytes, to drive the expression of S100A4." (PMID 30980596, 2019).
breast carcinoma (continued). "Although the accuracy of this statement must be questioned given the small number of MMHN cohorts, the protective role of KLK6 has been described before in other tumor entities such as breast cancer, and therefore seems to be highly dependent on the microenvironment and the tumor entity." (PMID 28671620, 2017). "KLK6 is thought to act on the TGFβ1 signal transduction pathway and thereby influence cell migration and motility, and KLK6 alters the expression of TGFβ1 in breast cancer cells." (PMID 22436421, 2012). "We present previously unknown pathways implicating KLK6 in breast cancer." (PMID 30980596, 2019). "Therefore, KLK6 affects the ability of breast cancer cells to colonize the lungs dose‐dependently." (PMID 30980596, 2019). "For the KLK6 + S100B‐S100A7, breast cancer patients with the lowest scores have longer long‐term survival as compared to patients with high scores." (PMID 30980596, 2019). "Two composite scores, KLK6 + S100B‐S100A7 and KLK6 + S100B‐S100A14‐S100A16, were generated to predict long‐term survival of breast cancer patients." (PMID 30980596, 2019). "By integrating proteomics and microarray data from breast cancer patients, we generated two composite scores, KLK6 + S100B‐S100A7 and KLK6 + S100B‐S100A14‐S100A16, to predict long‐term survival of breast cancer patients." (PMID 30980596, 2019). "It was subsequently supported by the findings that KLK6 was significantly up-regulated by norgestrel, oestradiol and DHT in the breast cancer cell line BT474." (PMID 17242704, 2007). "The KLK6 gene (previously known as zyme, protease M, neurosin, PRSS6) was originally cloned based on its lower expression in metastatic breast cancer compared to primary cancer and normal tissue." (PMID 14710225, 2004). "Of these genes, PTK7, KLK6 and LIMCH1 have interesting links with breast cancer; PTK7 is a catalytically inactive receptor tyrosine kinase in the Wnt signalling pathway, and a PTK7 targeted antibody–drug conjugate has been shown to reduce tumour-initiating cells." (PMID 38036593, 2023). "Next, we determined the effect of KLK6 inhibition on tumour cell proliferation and migration and treated a panel of PDAC cell lines with the same APPI-4M concentration (100 nM), which reduced the migratory behaviour of breast cancer cells in our earlier study." (PMID 34439122, 2021). "In breast cancer, reduced KLK6 mRNA levels have been found relative to noncancerous tissue, but in TNBC and HER2‐positive cancer, there is an overexpression of KLK6 mRNA and KLK6 levels constitute an unfavorable marker for breast cancer." (PMID 30980596, 2019). "We have previously shown that kinin B1R favors the malignant phenotype of breast cancer cells (MCF-7, T47D, and ZR-75-1 cells) because its stimulation by B1R agonists induces cell proliferation and secretion of metalloproteinases-2 and -9, and of kallikrein-related peptidase 6, among other effects." (PMID 33117280, 2020). "How KLK6 expression is regulated in breast cancer is not fully elucidated." (PMID 30980596, 2019). "In particular, sensitivity of IgYs for detection of endogenous KLK6 and lack of crossreactivity with other KLKs and unrelated proteins was assessed by analyzing whole cell lysates and supernatants isolated from MDA-MB-468 breast cancer cell line that expresses the KLK5, KLK6 and KLK10 proteins." (PMID 23216878, 2012).
colon carcinoma (32 papers, 2009 to 2026). "Additionally, KLK6 has been found up-regulated both in tumor specimens and serum of patients with colon cancer and high KLK6 expression was associated with poor prognosis." (PMID 23216878, 2012). "Correlations between levels of PRSS3 and PRSS22 mRNAs and CEA, CXCL16, CXCL17, GPR35 V2/3, LGR5, LGR6 and KLK6 mRNA levels in lymph nodes of colon cancer patients." (PMID 40909962, 2025). "As has been previously reported, elevated KLK6 expression can accelerate the EMT in colon cancer cells and can activate the signal transduction pathways controlling cell invasion and metastasis via the Transforming Growth Factor β2 (TGF-β2) signaling pathway." (PMID 39594797, 2024). "Using in vitro and in vivo colon cancer models, we also showed that KLK6 expression is upregulated by the mutant K-RAS oncogene." (PMID 39594797, 2024). "Ceacam5, Klk6, Slc35d3, Postn, and Muc2 mRNA analysis improves the detection of tumor cells in the lymph nodes of colon cancer patients." (PMID 37996411, 2023). "We showed that, although many KLKs transcripts are upregulated in colon cancer-derived cell lines, KLK6, KLK10, and KLK11 are the most highly secreted proteins." (PMID 35883559, 2022). "These experiments suggest that KLK6 activates the MAP-kinase pathway in colon cancer cells at the concentrations equivalent to those of PARs agonists." (PMID 35883559, 2022). "Minimal if any staining for KLK6 was observed in epithelial cells of the normal appearing human colonic mucosa resected at more than 10 cm away from the neoplastic colon cancer lesions." (PMID 35883559, 2022). "Elevated expression of KLK6 is a common feature in many human malignancies, including colon cancer progression." (PMID 35883559, 2022). "Since we have previously shown that PAR activation plays a pivotal role in extracellular-regulated kinase (ERK1/2)-induced activity in colon cancer, we next investigated the effect of KLK6 on ERK1/2 phosphorylation in HT-29 cells." (PMID 35883559, 2022). "In this study, we showed for the first time that KLK6 has a role in colon cancer spheroids formation." (PMID 35883559, 2022). "KLK6 suppression in HCT-116 colon cancer cells decreased the colony formation, increased cell adhesion to extracellular matrix proteins, and reduced spheroid formation and compaction." (PMID 35883559, 2022). "Herein, we evaluated the expression and cellular functions of KLK6 in colon cancer-derived cell lines and in clinical samples from CRC patients." (PMID 35883559, 2022). "Herein, we demonstrate the expression and secretion of KLK6 in colon cancer cell lines and in CRC tumors resected from patients in contrast to the absence of KLK6 expression in normal colorectal tissues." (PMID 35883559, 2022). "Our findings highlighted the role of KLK6 in supporting an aggressive phenotype in colon cancer in vitro." (PMID 35883559, 2022). "Another analysis based on the TCGA found that KLK6 overexpression correlated with c-MYC expression and both are associated with overall survival of patients with colon cancers." (PMID 35883559, 2022). "As previously reported KLK6 expression in colon cancer can be induced by the major colon cancer driver gene, the oncogenic (K-RAS)." (PMID 35883559, 2022). "KLK6 mRNA transcript levels were investigated in 15 human colon cancer cell lines by RT-PCR analysis." (PMID 35883559, 2022). "In this study, we show that from all the overexpressed KLKs in colon cancer-derived cell lines, KLK6 was found to be among the major highly expressed kallikrein-related peptidases in vitro and capable to control cell proliferation through PAR2 signaling." (PMID 35883559, 2022). "To evaluate expression of KLK6 in colonic tumors in vivo, we next performed IHC analysis of KLK6 expression in colon cancer samples from patients with adenocarcinomas and normal colonic epithelium." (PMID 35883559, 2022).